GAS5 (growth arrest specific 5)
Diseases named in the same sentence as GAS5 in open-access papers (continued):
Sharing a sentence is not in itself a finding about the gene and the disease.
tumor (continued). "In addition, we demonstrated that GAS5 downregulation correlated with larger tumour size and more advanced tumour-node-metastasis (TNM) staging in the serum of CRC patients." (PMID 28099146, 2017). "GAS5 could positively regulate PTEN-induced tumor-suppressor pathway via miR-32-5p, thereby suppressing PC metastasis." (PMID 29225772, 2017). "However, the biological role and functional mechanism of GAS5 in tumour genesis needs further clarification." (PMID 28099146, 2017). "Additionally, lncRNA growth-arrest-specific 5 (GAS5) plays tumor-suppressive roles in PC cells, whereas NEAT1, MALAT1, HOTTIP and HOTAIR exert oncogenic roles in PC cells." (PMID 29137412, 2017). "Thus, it is possible that downregulation of GAS5 additionally activates an Erk1/2/NF-κB pathway to enhance the inflammatory effects in tumour cells." (PMID 28099146, 2017). "Growth arrest-specific 5, localized at chromosome 1q25.1, could transcribe a tumor-suppressive lncRNA in human cancers." (PMID 28293170, 2017). "For GAS5, we observed neither significant differential expression between tumour and benign tissues nor associations of expression with histopathological parameters or prognosis." (PMID 28430799, 2017). "Similarly, miR221/222 have an oncogenic role (by targeting TIMP2 and semaphorin 3B) and the LncRNA GAS5 (Growth arrest-specific 5), which targets miR-222, functions as a tumor suppressor." (PMID 29261132, 2017). "The striking difference in both the expression and function of these variants suggests differing roles in cell regulatory pathways, and may explain why GAS5 has alternately been described as both a tumor suppressor and oncogene in various cancers." (PMID 28035057, 2017). "The results showed that sample source and tumor types were unlikely to affect the diagnostic accuracy of GAS5." (PMID 29029523, 2017). "GAS5 participates in tumor development by interacting with diverse molecular partners." (PMID 29029523, 2017). "LncRNA GAS5 is a rising star among tumor-suppressive lncRNAs." (PMID 28977945, 2017). "GAS5 exerts complementary effects on cell proliferation (inhibitory) and apoptosis (stimulatory), and taken together, these cellular mechanisms likely form the basis of its tumor-suppression action." (PMID 28293170, 2017). "All in all, the study indicated that the decrease in GAS5 expression may contribute to OSCC tumor pathogenesis and serve as a potential target for cancer therapy." (PMID 29296179, 2017). "In addition, cancer patients with low GAS5 expression in tumor tissues were more prone to develop LNM and DM." (PMID 29029523, 2017). "Overall results showed that decreased GAS5 expression associated with unfavorable overall survival (OS) (HR = 2.50, 95%CI: 1.85–3.38, P < 0.001) and disease-free survival (DFS) (HR = 2.24, 95%CI: 1.58–3.18, P < 0.001) in several tumor types." (PMID 29029523, 2017). "Knockdown of GAS5 promoted cell proliferation and tumor growth in vivo." (PMID 27034004, 2016). "Previously, the well-documented GAS5 was generally considered as a tumor suppressor." (PMID 27391432, 2016). "For instance, tumor suppressors GAS5 and MEG-3 were downregulated by less than 2-fold in tumors." (PMID 27323410, 2016). "Together, these findings support a tumour suppressor role for GAS5 lncRNA in vivo." (PMID 26198250, 2015). "A high level of HEIH has been found significantly associated with HBV-related HCC recurrence (HR = 2.1; 95% CI: 1.2–3.7), while another study found HCC patients with lower levels of GAS5 in tumor tissue had a worse overall survival than patients with higher expression (HR = 2.4; 95% CI: 1.6–4.1)." (PMID 26378581, 2015). "Moreover, functional studies support a more direct tumour suppressor role for GAS5 lncRNA, as will be discussed in detail in the next section." (PMID 26198250, 2015).
tumor (continued). "Functional studies have further shown that GAS5 lncRNA both inhibits the proliferation and promotes the apoptosis of multiple cell types, and that together these cellular mechanisms of action are likely to form the basis of its tumour suppressor action." (PMID 26198250, 2015). "Moreover, forced expression of GAS5 lncRNA in such cells inhibits tumour growth in xenograft models, mirroring clinical findings." (PMID 26198250, 2015). "GAS5 expression was predominantly identified in quiescent tumor cells." (PMID 24885398, 2014). "qRT-PCR analysis of GAS5 expression was then performed in selected tumor tissues." (PMID 24884417, 2014). "By in situ hybridization of MPM tissue we observed a high GAS5 expression in quiescent tumor cells." (PMID 24885398, 2014). "While GAS5 predominated in degenerating tumor cells in all patients, it can be speculated that patients who responded to chemotherapeutic intervention demonstrated even further elevated levels of this tumor suppressor than non-responders, perhaps influencing an extension in overall survival." (PMID 38258133, 2024). "Notably, GAS5 was found to be overexpressed in M1-type macrophages compared to M2-type macrophages and was shown to block immune escape and cell proliferation by exerting the tumor-suppressive functions of M1 macrophages in CRC." (PMID 37760852, 2023). "As for OV, previous studies indicated that regulation of PRGs, including HOTTIP, α-NETA, and LncRNA GAS5 in tumor cells could promote pyroptosis by inducing inflammasome formation, in order to inhibit OV progression, which could be used as a potential target for tumor therapy." (PMID 37730669, 2023). "Furthermore, since lower GAS5 expression indicates poor prognosis, growth-stop-specific 5 (GAS5), a tumor suppressor lncRNA in OC, may be useful for assessing the patient’s response to first-line therapy." (PMID 36902032, 2023). "Interestingly, the tumor increases angiogenesis by suppressing the amount of GAS5 in its exosomes." (PMID 36905871, 2023). "Furthermore, the anti-tumor ability of GAS5-overexpression could be inhibited partly by let-7e and miR-125a inhibitors, individually or jointly, and the effect of the let-7e inhibitor was stronger than that of the miR-125a inhibitor." (PMID 36106122, 2022). "Notably, the invasive ability of the tumor may be eliminated through a combination of upregulated GAS5 and miR-135b, exhibiting increased RECK, and the expression and activity of MMP-2 are insufficient." (PMID 35837102, 2022). "LncRNA GAS5, which was originally found to accumulate in growth-arrested cells, has been reported to serve as a tumor suppressor gene in many cancers, and its expression was often downregulated in various cancers, and its overexpression inhibited tumorigenesis, tumor progression and drug resistance." (PMID 35435104, 2022). "GAS5 lncRNA can not only inhibit the proliferation of various types of tumors, but also promote their apoptosis, and the mechanism of these cells may jointly constitute the basis of their tumor inhibition." (PMID 35813295, 2022). "It transpires that the GAS5 effect of inhibiting tumor growth can be partly attributed to its effect on the level of cellular ROS, but further research is needed to conclude whether this is achieved by augmenting ROS expression and promoting apoptosis or by mitigating the pro-growth effect of ROS." (PMID 36077530, 2022). "Thus, GAS5 induces a cell cycle arrest in the G0–G1 phase and acts as a tumor suppressor." (PMID 35103065, 2022). "Furthermore, univariate Cox proportional hazards regression showed that age (P = 0.004), tumor stage (P < 0.001), tumor grade (P < 0.001), MIR205HG (P < 0.001), and GAS5 (P = 0.005) were significantly associated with PFS of NMIBC patients, whereas sex (P = 0.624) had no significant influence." (PMID 33987102, 2021). "Therefore, it is widely accepted that GAS5 acts as a tumor suppressor." (PMID 34439281, 2021).
tumor (continued). "Similarly, GAS5 works as a tumor suppressor lncRNA in HCC cells via GAS5/miR-182/ANGPTL1 axis." (PMID 34885213, 2021). "Importantly, GAS5 is widely considered as a tumor suppressor." (PMID 34625583, 2021). "Indeed, GAS5 may sequester hsa-miR-21-5p in NSCLC tumor tissues and the cell lines (NCI-H460, A549, NCI-H1299, H460, SK-MES-1, H157, and H358)." (PMID 32438606, 2020). "Our study found that with cisplatin injection, the tumour volumes in the GAS5 overexpression group presented a declining trend, which was not due to the influence of proliferation but rather apoptosis, indicating that GAS5 overexpression enhanced the cisplatin sensitivity of xenograft tumours." (PMID 32661236, 2020). "Therefore, the axis of GAS5/IER3/miR-106b can promote the sensitivity of tumor cells to radiation." (PMID 32122355, 2020). "Thus, GAS5 up-regulation confers tumor cell proliferation inhibition." (PMID 33076450, 2020). "Similarly, GAS5 was found to be down-regulated in transitional cell carcinomas of the urinary bladder, and its down-regulation was found to be positively correlated with higher pathological grades of the tumor." (PMID 33076450, 2020). "However, there are some reports referring to GAS5 as a significant gene in the tumor’s progression." (PMID 33076450, 2020). "With the rise of studies on the functional properties of lncRNAs, it has been verified that lncRNAs can efficiently affect the biological processes of cancers, some of which may serve as tumor or metastasis inhibitors, such as GAS5 and MEG3, while others may promote oncogenesis, such as SChLAP1." (PMID 32694942, 2020). "Furthermore, tumor subcutaneous growth and lung metastasis xenograft mice models demonstrated that overexpression of YTHDF3 resulted in dramatic acceleration of the tumor growth rate and lung colonization ability, which reversed the tumor suppression resulting from GAS5 overexpression." (PMID 31619268, 2019). "Furthermore, multivariate COX regression analysis in the present study showed that Gas5 expression, distant metastasis, tumor differentiation and TNM staging could serve as independent prognostic factors for CRC." (PMID 29308053, 2018). "Additionally, the adverse outcome of the TaT1 patients with GAS5 loss revealed to be independent of tumour stage and grade, EORTC-risk stratification, age and gender." (PMID 30374124, 2018). "However, we still provide strong evidence for the tumor suppressor role of lncRNA GAS5." (PMID 29207621, 2017). "Moreover, increasing evidence suggested that GAS5 functions as a tumour suppressor." (PMID 28099146, 2017). "Consequently, enhancing cellular GAS5 lncRNA levels in tumour tissue may not only suppress the growth of such tumours but also enhance tumour cell killing by therapeutic agents, thereby improving patient outcomes." (PMID 26862727, 2016). "Finally, tumour-suppressive lncRNAs such as GAS5 have been shown to be downregulated in cancer." (PMID 25813522, 2015). "Consistently, the downregulation of endogenous GAS5 inhibits apoptosis and maintains a more rapid cell cycle, indicating that GAS5 expression is both necessary and sufficient for normal growth arrest in human cells, and it suggests that GAS5 can act as a tumor suppressor." (PMID 23383264, 2013). "The downregulation of several lncRNA with tumour suppressor activity such as BGL3, GAS5, MEG3, NBAT-1 and PTENP1 have been reported in different cancers." (PMID 39912983, 2025). "Most recently, the upregulation of GAS5 has been demonstrated to repress miR-135b-5p, resulting in the upregulation of the adenomatous polyposis coli (APC) gene, a known tumor suppressor, through its regulation of the Wnt/β-catenin pathway." (PMID 39941145, 2025).
tumor (continued). "Various lnRNAs exhibited differential expression in tumor suppressive lncRNAs expression were downregulated such as CASC2, GAS5, MEG3, FER1L4, and LINC00672 expression were in EC tissues in contrast to normal tissues." (PMID 39912983, 2025). "The sponging of miR-23a by lncRNA GAS5 relieves WT1 from translational suppression, allowing it to exert its tumour inhibiting function to halt tumour progression." (PMID 39736850, 2025). "The long non-coding RNA (lncRNA) growth arrest-specific 5 (GAS5) plays a vital role in the emergence of the CD133+ population, representing tumor-initiating cells that result in tumor relapse." (PMID 39859324, 2025). "Analysis of the methylation level of the GAS5 promoter using TCGA data in the UALCAN database showed statistically significant differences (p < 0.0001) between normal and primary tumor samples in CHOL, KIRC, and LIHC." (PMID 39958058, 2025). "Knockdown of GAS5 (si-GAS5), SMARCA4 (si-SMARCA4) or overexpression of miR-423-3p mimics significantly inhibited tumor cell growth and proliferation rates to similar degrees in Hep3B, Huh7 and SNU-449 cell lines." (PMID 40451925, 2025). "Therefore, GAS5 may serve a crucial role as an important tumor suppressor in tumor therapy." (PMID 39830506, 2024). "Collectively, our findings suggest a complex role for GAS5 in HCC, potentially playing a part in tumor initiation but also exerting a protective effect against disease progression." (PMID 39609501, 2024). "Growth arrest-specific transcript 5 (GAS5) is located at chromosome 1q25 and acts as a tumor suppressor." (PMID 39114567, 2024). "GAS5 upregulation led to MST1 protein overexpression and increased YAP and TAZ phosphorylation, Hippo signaling activation, and inhibited tumor growth in vivo." (PMID 38226210, 2024). "Mechanistically, GAS5 recruits the transcription factor E2F4 to the PARP1 promoter and attenuates its transcription, thereby inhibiting the MAPK pathway and tumor progression." (PMID 38725621, 2024). "Methylated GAS5 transcripts are degraded by the m6A reader YTHDF3, which increases expression of YAP and in turn drives tumor progression." (PMID 39198884, 2024). "While a similar GAS5 distribution pattern was apparent in all GBM patients, those that responded to temozolomide revealed significantly higher levels of this tumor suppressor." (PMID 38258133, 2024). "For example, GAS5 has been reported to have prognostic value in CRC, where GAS5 regulates the transport and decay of YAP, an oncogene responsible for tumor progression in the disease." (PMID 39198884, 2024). "LncRNA GAS5 blocks the miR-222–3p/PTEN axis, which stops M2 macrophage polarization and tumor metastasis." (PMID 39257589, 2024). "Regarding downregulated lncRNAs, GAS5 and PCAT18 have been inversely correlated with advanced TNM stage and greater tumor size, respectively." (PMID 37047267, 2023). "Recent evidence suggests that lncRNA growth arrest-specific transcript 5 (GAS5) is an antioncogene in diverse tumors, and GAS5 enhanced the sensitivity of tumor cells to chemotherapy or radiotherapy." (PMID 37993867, 2023). "In vitro and in vivo studies have demonstrated that decreased GAS5 expression in human HCC cell lines induces cell proliferation and migration, thus indicating the role of GAS5 in tumor suppression and as a therapeutic target in HCC." (PMID 37296859, 2023). "Semi-quantitative PCR of our tumor, clone 5, and MEF cells showed a clear upregulation of GAS5 expression after 4-OHT treatment." (PMID 37349371, 2023). "In contrast, other lncRNAs such as the growth arrest-specific transcript 5 (GAS5), the maternally expressed gene 3 (MEG3), and the NF-kB interacting lncRNA (NKILA) function as tumor suppressors, inhibiting proliferation and tumor growth when up-regulated." (PMID 36827545, 2023). "As a tumor suppressor in CC, the m6A site of GAS5 mRNA was recognized and silenced by YTHDF2, which promoted the proliferation, migration, and invasion of tumor cells." (PMID 37951987, 2023).
tumor (continued). "H19, TCL6, CAM1-AS1, GAS5 and LOC389332 act as tumor-suppressors, and are instead, downregulated; in particular, H19 and TCL6 are negatively correlated with TNM stage, lymph node metastases and distant metastases." (PMID 37370817, 2023). "Since GAS5 functions as a ceRNA for miR-21, and miR-21 promotes tumor proliferation and invasion by targeting PTEN, the low levels of GAS5 in SKBR-3/Tr cells are related to low PTEN levels, favoring the aggressive properties of cancer cells." (PMID 37444428, 2023). "In breast cancer, a variety of non-coding RNAs have been found to work as tumor suppressors or tumor-promoting effectors, such as XIST, HOTAIR, GAS5, MALAT1, etc.." (PMID 36230738, 2022). "Recent findings revealed that GAS5 is suppressed in several different cancers, and the downregulation of GAS5 was accompanied by the advanced TNM stage and large tumor size in CRC." (PMID 36699052, 2022). "The tumour suppressive, AKT/mTOR-regulating role of GAS5 in Pca was further confirmed by in vivo xenograft model." (PMID 35159022, 2022). "Bioinformatics analysis showed that miR-21 possesses more binding sites in GAS5 than other miRNAs, and miR-21 was upregulated in CRC tissues, which inhibited tumor progression in CRC cells." (PMID 36062165, 2022). "LncRNA GAS5 can promote the degradation and phosphorylation of YAP, thus inhibiting the occurrence of tumours." (PMID 36324258, 2022). "The overexpression of GAS5 can promote the reduction in miR-21 expression, increase the levels of RECK, and increase tumor cell apoptosis after radiotherapy." (PMID 35241975, 2022). "In vivo lncRNA GAS5 overexpression inhibited GH3 cell tumor growth, while miR-27a-5p mimic or silenced CYLD attenuated the effect of lncRNA GAS5 on GH3 cell tumor growth." (PMID 35435104, 2022). "GAS5 was significantly decreased in tumor tissues and CRC cells, and the low expression of CAS5 in CRC promoted tumor metastasis and decreased the survival of patients." (PMID 36062165, 2022). "Meanwhile, growth arrest-specific transcript 5 (GAS5), located at chromosome 1q25, has been acknowledged to function as a tumor suppressor in numerous cancers." (PMID 35340210, 2022). "LncRNA GAS5 expression was reported to be decreased in mononuclear cells of CLL patients in comparison to healthy controls, implying its tumor suppressor function in CLL." (PMID 36362925, 2022). "LncRNA GAS5 was originally identified as part of a group of genes expressed during the growth arrest phase of NIH3T3 cells and has been characterized as a tumor suppressor." (PMID 36672566, 2022). "In LSCC, GAS5 inhibited the viability of AMC-HN-8 cells and induced apoptosis, acting as a tumor suppressor by regulating the miR-26a-5o/ULK2 axis." (PMID 35978835, 2022). "Like GAS5, MEG3, an imprinted lncRNA with maternal-specific expression, has been shown to act as a tumor suppressor in several cancers by being in strong functional connection with epigenetic machinery." (PMID 36230680, 2022). "GAS5 is a tumor suppressor factor that inhibits proliferation, EMT, invasion, and metastasis of tumor cells." (PMID 35103065, 2022). "Growth arrest-specific transcript 5 (GAS5) is down-regulated in several cancers and recognized as a tumor suppressing lncRNA." (PMID 33777808, 2021). "The juggling tumor suppressor ncRNA category includes miR-16, miR-34a, miR-142-3p, lncRNA CCAT1, lncRNA COX2, lncRNA GAS5, and lncRNA NIFK-AS1 while the category of juggling oncogene includes miR-503 and lncRNA MALAT1." (PMID 33522932, 2021). "Second, relative expression levels of GAS5 were evaluated in 41 pairs of NSCLC and tumor adjacent tissue samples." (PMID 33418541, 2021). "To summarize, GAS5, MEG3, LINC0111, and LINC00261 are tumor-suppressors in PDAC that act via inhibition of EMT." (PMID 34820419, 2021). "In TNBC, multiple lncRNAs had been identified to regulate EMT pathways and tumor invasion via interacting with various molecules, such as LINC01638, GAS5, UCA1, ARNILA, and NNT-AS1." (PMID 34873403, 2021).